RNU7-183P (RNA, U7 small nuclear 183 pseudogene)
Gene: Small nuclear RNA gene on chromosome 1 (185,434,244 to 185,434,305, forward strand). Ensembl gene ENSG00000252407.
Homologues: Orthologues: chimpanzee U7 (100% identical), macaque U7 (94% identical). Paralogues in human: RNU7-56P (84% identical), RNU7-172P (82% identical), RNU7-55P (82% identical), U7 (82% identical), RNU7-10P (81% identical), RNU7-140P (81% identical), RNU7-2P (81% identical), RNU7-34P (81% identical), RNU7-4P (81% identical), RNU7-84P (81% identical), RNU7-1 (79% identical), RNU7-124P (79% identical), and 142 more.